ELF1 (E74 like ETS transcription factor 1)
Diseases named in the same sentence as ELF1 in open-access papers (continued):
Sharing a sentence is not in itself a finding about the gene and the disease.
acute promyelocytic leukemia (1 paper, 2022). An aggressive form of acute myeloid leukemia (AML), characterized by arrest of leukocyte differentiation at the promyelocyte stage, due to a specific chromosomal translocation t(15;17) in myeloid cells. "Based on our analysis of the Beat AML dataset, we observe a positive correlation between adverse overall survival and high FLI1 and ELF1 transcript levels in all non-acute promyelocytic leukemia patients, especially in CN-AML where MEIS1 levels are high." (PMID 35624144, 2022).
co-infection (1 paper, 2008). "Elf-1 expression was statistically equivalent in the HPV alone and HPV/HIV-1 co-infection, suggesting that HIV-1 per se was not modulating its expression." (PMID 18840277, 2008).
E. coli infection (1 paper, 2023). "Together, our findings suggest that DRAM1 induced by ELF1 could upregulate autophagy to resist bacterial infection and promote glycolysis (presumably through its association with GAPDH) for autophagic energy supply during E. coli infection." (PMID 37919720, 2023).
epilepsy (1 paper, 2021). A brain disorder characterized by episodes of abnormally increased neuronal discharge resulting in transient episodes of sensory or motor neurological dysfunction, or psychic dysfunction. "It should be noted, however, that the ETS expression profile is also different in epilepsy; ELF1, ELK1, ELK4, ETS1, ETS2, and ETV1 are expressed at higher levels than ELF4, ELK3, and ETV4, and there is also variability in expression among different types of epilepsy." (PMID 33671331, 2021).
HIV-1 infection (1 paper, 2010). The type species of lentivirus and the etiologic agent of acquired immunodeficiency syndrome (AIDS). "Neither the role of Elf-1 in FcRγ expression in NK cells nor the effect of HIV-1 infection on Elf-1 expression is known." (PMID 20224795, 2010).
influenza (1 paper, 2022). An acute viral infection of the respiratory tract, occurring in isolated cases, in epidemics, or in pandemics; it is caused by serologically different strains of viruses (influenzaviruses) designated A, B, and C, has a 3-day incubation period, and usually lasts for 3 to 10 days. "Interestingly, ELF1 transcriptionally program cells with potent antiviral activity and ETV7 targeted antiviral ISGs crucial for IFN-mediated control of viruses, including influenza and SARS-CoV-240,41." (PMID 35017649, 2022).
intervertebral disc degeneration (1 paper, 2025). "Importantly, our comparative analysis revealed that Elf1 knockout (KO) significantly attenuates the degenerative progression of AF tissue when compared to aged mouse disc tissues, suggesting a potential therapeutic target for intervertebral disc degeneration." (PMID 40467575, 2025).
liver cirrhosis (1 paper, 2022). "Some of the important hub genes in the BisoGenet-derived PPI for liver cirrhosis and HCC diseases were E2F1, TAL1, CEBPB, ELF1, RAD21, CEBPB, and MYC." (PMID 35265561, 2022).
ovarian carcinoma (1 paper, 2018). A malignant neoplasm originating from the surface ovarian epithelium. "However, previous studies reported that both ELF-1 and LAIR-1 expression were significantly associated with histological grade of ovarian carcinoma, while we overexpressed ELF-1 in HO8910 cells did increase LAIR-1 expression." (PMID 29915163, 2018).
peripheral nerve injury (1 paper, 2022). Injury to a peripheral nerve. "In the present study, we identified a nerve injury–specific lncRNA and reported its upregulation triggered by an elevation of the transcription factor ELF1 in injured DRGs after peripheral nerve injury." (PMID 35775484, 2022).
psoriasis (1 paper, 2021). An autoimmune condition characterized by red, well-delineated plaques with silvery scales that are usually on the extensor surfaces and scalp. "In spite that these results must be validated in vitro and in vivo with a functional genomics approach, we propose FOXP2, RUNX2, NR2F1, ELF1 and HESX1 transcription factors (those with the highest FIF on each gene) as novel drug targets for psoriasis." (PMID 33898962, 2021).
sarcoma (1 paper, 2020). A usually aggressive malignant neoplasm of the soft tissue or bone. "FOXO1 was most strongly associated with sarcoma (DOID:1115, with ELF1), and squamous cell carcinoma (DOID:5520, with ELF3) (k-mer = WAAACAGGAAG for both terms; mean k-mers Z-score > 5)." (PMID 31913281, 2020).
Sepsis (1 paper, 2025). Sepsis is defined as life-threatening organ dysfunction caused by a dysregulated host response to infection. "The present study validated that the mRNA expression of ELF1, which was predicted as a TF of the hub genes, was upregulated in patients with sepsis and in a mouse model of CLP." (PMID 40821971, 2025). "Additionally, the expression of the predicted TF ELF1 was confirmed through RT-qPCR analysis in peripheral blood monocytes from patients with sepsis and mice after CLP." (PMID 40821971, 2025). "By integrating the predictive results from five online miRNA websites, the current study proposed a potential lncRNA-miRNA-mRNA pathway: the NEAT1-hsa-miR-495-3p-ELF1 pathway, which may exert an important influence on the pathogenesis of sepsis." (PMID 40821971, 2025). "This study identified four hub genes (CLEC4D, GPR84, S100A12, and HK3) with significant prognostic value in sepsis and predicted a ceRNA network (NEAT1-hsa-miR-495-3p-ELF1) regulating their expression." (PMID 40821971, 2025). "Based on the ceRNA hypothesis, one downregulated miRNA and one upregulated lncRNA previously reported in sepsis were selected, resulting in the proposal of the following ceRNA network: NEAT1-Homo sapiens (hsa)-miR-495-3p-ELF1." (PMID 40821971, 2025).
viral infection (1 paper, 2019). "To establish ELF1 as a component of the antiviral immune response, we determined its expression in different cell lines, primary cell culture systems, and a mouse model, upon interferon treatment, stimulation with pathogen-associated molecular patterns (PAMPs), or viral infection." (PMID 31682641, 2019). "Using microscopy to quantify viral infection over time, we found that ELF1 inhibits eight diverse RNA and DNA viruses after multi-cycle replication." (PMID 31682641, 2019). "A molecular mechanism for such a switch might be through interaction of ELF1 with a protein that is only present (or active) upon viral infection." (PMID 31682641, 2019). "Thus, we propose that a first round of viral infection is required for ELF1 to protect cells from subsequent rounds of infection." (PMID 31682641, 2019).
cancer (16 papers, 2008 to 2025). A tumor composed of atypical neoplastic, often pleomorphic cells that invade other tissues. "Further, we showed that RICTOR regulates three transcription factors, like ZFX, CTCF, and ELF1, that can further regulate multiple genes/enzymes, including some from the sphingolipid and ganglioside pathways in a cell-type and cancer-context-dependent manner." (PMID 40934285, 2025). "Meanwhile, bioinformatics has deconstructed the probable processes of CCT5 and ELF1, but further investigation will be needed to clarify their biological role and impact on the cancer microenvironment in future studies." (PMID 37953237, 2023). "Previous cancer studies indicate that ELF1 can be a tumor suppressor or an oncogene, depending on the cell type." (PMID 30603056, 2018). "Here we report that ELF1 can have tumor suppressive functions in prostate epithelial cells and that ELF1 levels are negatively correlated with cancer progression within this tissue." (PMID 30603056, 2018). "ELF1 belongs to the E26 transformation specific (ETS) family of transcription factors which regulate the expression of genes involved in several processes that are considered the hallmarks of cancer." (PMID 37066112, 2022). "Previous studies on ELF1's function in cancer indicate both oncogenic and tumor suppressive roles." (PMID 30603056, 2018). "A series of in vitro experiment suggests that ELF-1- and/ or STAT1-dependent Lin28b regulation is responsible for Let-7 induction in Fhit-expressing cancer cells." (PMID 33437205, 2021). "We compared the function of ELF2 isoforms ELF2A and ELF2B with other ELF subfamily proteins ELF1 and ELF4 in primary and cancer cell lines using proliferation, colony-forming, cell cycle, and apoptosis assays." (PMID 28351373, 2017). "Notably, among the 14 TFs whose binding sites were sex-dependently enriched across different cancers, eight were previously found to be enriched among sex-biased expressed genes, including SP1, ETV1, ELF1, E2F1, CREB1, CTCF, SIX2, and SOX2." (PMID 39716176, 2024). "Also, a series of in vitro experiments suggests that ELF-1- and/or STAT1-dependent Lin28b regulation is responsible for Let-7 induction in Fhit-expressing cancer cells." (PMID 33437205, 2021). "Comparison of other ELF family members showed ELF1 and ELF4 were also more highly expressed in AML than all other cancers, suggesting that they may play a role in AML." (PMID 28351373, 2017). "However, until now, although more than 10 different ETS transcription factors have been found in human cancers, only a few ETS family members such as Elf-1, PEA3, ESE1 have been reported as potential HER2 transactivators." (PMID 27517321, 2016). "Furthermore, we analyzed our original chromatin accessibility data,and found that the DNA binding motifs of ELF1, JUND, and SPI1, which arepotential transcription factors of PARP10, NIPAL1 and ZYG11B in CRC tissues, arespecifically open in cancer tissues compared with adjacent tissues." (PMID 41020586, 2025). "Several genes (B2M, EIF2B1, ELF1 and PSMC4; type 1 EC, and YWAZ, UBC, and PGK1; type 2 EC) were not identified in the combinations of five best genes for the two cancer sub-types (this study) suggesting that the transcriptome of these two EC sub-types may in fact be very different." (PMID 32439920, 2020). "Elf-1 expression did increase in CIN II/III and carcinoma lesions compared to the negative controls in HPV alone infected cervices and did reach statistical significance, suggesting that molecular events in the more progressed HPV infected cervices was increasing Elf-1 expression." (PMID 18840277, 2008).
tumor (14 papers, 2008 to 2025). "ELF1 has been implicated in transcription regulation of several tumor-promoting genes including Tie2, MEIS1, CCL2, LUCAT1." (PMID 32795319, 2020). "ELF1, encoding a member of ETS family transcription factors with vital roles in tumorigenesis, acts as a tumor suppressor." (PMID 36430822, 2022). "This function, along with ELF1's ability to repress cell migration at ETS/AP-1 sites, provides a potential mechanism for tumor suppressive functions of ELF1." (PMID 30603056, 2018). "In contrast to these oncogenic roles, ELF1 nuclear expression is negatively correlated with histological grading and tumor size in breast ductal carcinomas." (PMID 30603056, 2018). "Genome-wide mapping in cell lines indicated that ELF1 has two distinct tumor suppressive roles mediated by distinct cis-regulatory sequences." (PMID 30603056, 2018). "Both ELF2A and ELF2B uniquely interact with the haemopoietic transcriptional co-regulator and proto-oncogene LMO2 whilst ELF1 specifically interacts with the tumour suppressor RB1." (PMID 28351373, 2017). "The Elf-1 factor is a transcription factor that regulates a number of inducible lymphoid-specific genes and also in the development of tumor angiogenesis." (PMID 18840277, 2008). "high PLP2+ Tumor EPCs score group highly expressed ATF6, ELF1, ERG and PLAGL1 genes, while low PLP2+ Tumor EPCs score group highly expressed ATF5, TBX21, SPIB, LHX2 and JUND genes." (PMID 38482016, 2024). "We also observed that a number of genes with tumor suppressor function (GPRC5A, ELF1, NAB2, Sema4D, ACPP, MAP2, RUNX1) persistently remained downregulated in response to radiation exposure." (PMID 23216862, 2012). "There was a significant increase in Elf-1 expression in HPV+/HIV- women with CIN II/III and tumor (average of cells/mm2 in CIN I: 63.8; CIN II/III: 115.7 and tumor: 112.0, p = 0.005), in comparison to controls." (PMID 18840277, 2008).
infection (4 papers, 2019 to 2024). The state of being infected such as from the introduction of a foreign agent such as serum, vaccine, antigenic substance or organism. "On day 7 of infection, the effector P14 T cell populations in the spleen that were deficient for Elf1 or Prdm9 displayed an increased frequency of memory precursor (KLRG1-CD127+) cells compared to the control population." (PMID 36156073, 2022). "Animals with reduced Elf1 lost significantly more body weight and exhibited significantly increased mortality; 100% of Elf1-knockdown animals succumbed to infection, as compared to 50% in either control group." (PMID 31682641, 2019). "A supplementary high-MOI infection experiment confirmed ELF1’s lack of inhibition during single-cycle replication." (PMID 31682641, 2019). "The O-GlcNAcylation of E74-like ETS transcription factor 1 (Elf-1) also negatively regulates TOLLIP expression in monocytes, which likely enhances monocyte’s responses to TLR activation; however, how this pathway is involved in a real life infection remains to be explored." (PMID 38718861, 2024). "Furthermore, at day 21 of infection, the memory T cell population was comprised of an increased proportion of TEM (CD62L-CD127+) when Elf1 expression was knocked down and an increased frequency TCM (CD62L+CD127+) and a decreased frequency of t-TEM (CD62L-CD127-) when Prdm9 was knocked down." (PMID 36156073, 2022).
bacterial infection (1 paper, 2023). "Additionally, ELF1 was significantly upregulated in C10_ULK1 cells from patients, indicating its potential role in response to bacterial infection." (PMID 37919720, 2023).
cardiovascular disease (1 paper, 2022). "We therefore genotyped hESCs for these common variants and identified 22 cell lines with a “universal donor” O blood type, a cell line (Elf1) likely resistant to HIV infection, and three cell lines carrying the APOE “e4/e4” risk haplotype for cardiovascular disease and AD." (PMID 35176222, 2022).
ELF1 also shares sentences with these, for which no sentence is quoted: endometrial carcinoma (3 papers); choroidal melanoma (2); inflammatory bowel disease (2); nasopharyngeal carcinoma (2); acute myeloid leukemia (1); alcoholic cirrhosis (1); aneurysm (1); autoimmune disease (1); cervicitis (1); Cirrhosis (1); Crohn disease (1); hematopoietic cancer (1); Hodgkins lymphoma (1); Hypertension (1); invasive carcinoma (1); ischemic stroke (1); lung carcinoma (1); multiple sclerosis (1); myocardial infarction (1); neurodevelopmental disorder (1); spinocerebellar ataxia type 1 (1); squamous cell carcinoma (1); T-cell lymphoma (1); teratoma (1).